LINC01117 (long independently transcribed non-coding RNA 1117)
Synonyms: uc.109
Gene: Long non-coding RNA gene on chromosome 2 (176,429,159 to 176,878,787, forward strand). Ensembl gene ENSG00000224577.
Diseases named in the same sentence as LINC01117 in open-access papers:
LINC01117 is named in the same sentence as 5 diseases in open-access papers, as found by Europe PMC text mining. Sharing a sentence is not in itself a finding about the gene and the disease. The quoted sentences say what the papers report.
breast carcinoma (1 paper, 2023). "Because miRNA-1246 overlaps an intron of LINC01117 (ENST00000652995.1), it is hard to predict how the decreased level of spliceosomal mir-1246 in breast cancer cells might affect the level of LINC01117 in breast cancer compared to normal cells, and further studies are required to resolve that." (PMID 37624034, 2023).
lung adenocarcinoma (1 paper, 2023). A carcinoma that arises from the lung and is characterized by the presence of malignant glandular epithelial cells. ", These experimental results suggest a close correlation between changes in LINC01117 expression and the expression levels of EMT-related markers such as E-cadherin, N-cadherin and Vimentin, strongly suggesting that LINC01117 may regulate lung adenocarcinoma progression by affecting EMT process." (PMID 37384755, 2023). "To investigate the role of LINC01117 in regulating the Hippo pathway in lung adenocarcinoma cells, we extracted total protein, cytoplasmic and nuclear proteins and assayed YAP1 levels in A549 cells with LINC01117 overexpression and knockdown." (PMID 37384755, 2023). "Overexpression of LINC01117 promoted the EMT process; while knockdown of LINC01117 inhibited the EMT process, suggesting that LINC01117 in lung adenocarcinoma cells may promote cell migration and invasion through the EMT process." (PMID 37384755, 2023). "This suggests that LINC01117 may regulate the activity of the Hippo pathway by altering the nuclear and cytoplasmic distribution of YAP1, which in turn induces the EMT process in lung adenocarcinoma cells and thus exerts a pro-cancer effect." (PMID 37384755, 2023).
lung carcinoma (1 paper, 2023). "In conclusion, LINC01117 as an oncogene promotes the development of lung cancer and through our study LINC01117 is expected to be a biomarker for lung cancer diagnosis and a potential therapeutic target." (PMID 37384755, 2023).
tumour (1 paper, 2022). "The expression levels of C15orf54, LINC01117 and SNHG3 varied between normal and tumour groups, and LINC01117 showed an up-regulated trend in tumours, while C15orf54 and SNHG3 showed a down-regulated trend in tumours." (PMID 35855425, 2022). "Among them, the expression levels of C15orf54, AL157935.1, LINC01117 and SNHG3 were different between normal and tumour groups, and all of them were up-regulated in tumours." (PMID 35855425, 2022).
LINC01117 also shares sentences with these, for which no sentence is quoted: cancer (2 papers).